AGXT2 (alanine--glyoxylate aminotransferase 2)
Description:
Multifunctional aminotransferase with a broad substrate specificity. Catalyzes the conversion of glyoxylate to glycine using alanine as the amino donor (By similarity). Catalyzes metabolism of not L- but the D-isomer of D-beta-aminoisobutyric acid to generate 2-methyl-3-oxopropanoate and alanine. Catalyzes the transfer of the amino group from beta-alanine to pyruvate to yield L-alanine and 3-oxopropanoate (By similarity). Can metabolize NG-monomethyl-L-arginine (NMMA), asymmetric NG,NG-dimethyl-L-arginine (ADMA) and symmetric NG,N'G-dimethyl-L-arginine (SDMA). ADMA is a potent inhibitor of nitric-oxide (NO) synthase, and this activity provides mechanism through which the kidney regulates blood pressure.
Synonyms: AGT2; BAIBA; DAIBAT
Tractability: PROTAC: its protein half-life has been measured.
Gene: Protein-coding gene on chromosome 5 (34,997,427 to 35,048,240, reverse strand). Ensembl gene ENSG00000113492.
Subcellular location: Mitochondrion
Pathways (Reactome):
Metabolism: Glyoxylate metabolism and glycine degradation; Pyrimidine catabolism
Gene Ontology:
Molecular function: (R)-3-amino-2-methylpropionate-pyruvate transaminase activity; alanine-glyoxylate transaminase activity; beta-alanine:pyruvate transaminase activity; alanine-oxo-acid transaminase activity; pyridoxal phosphate binding
Biological process: glycine biosynthetic process; glyoxylate catabolic process; L-alanine catabolic process; positive regulation of nitric oxide biosynthetic process
Cellular component: mitochondrion; mitochondrial matrix
Genetic constraint (gnomAD): Loss-of-function variants: 56 observed, 59.02 expected, observed/expected ratio (o/e) 0.95, 90% interval 0.76 to 1.18. The upper end of that interval is the gene's LOEUF score, 1.18, which puts it in group 5 of 6, group 1 being the genes least tolerant of losing a copy. Missense variants: 640 observed, 645.28 expected, observed/expected ratio (o/e) 0.99, 90% interval 0.93 to 1.06. Synonymous variants: 237 observed, 221.66 expected, observed/expected ratio (o/e) 1.07, 90% interval 0.96 to 1.19.
Homologues: Orthologues: chimpanzee AGXT2 (99% identical), macaque AGXT2 (96% identical), rabbit AGXT2 (86% identical), guinea pig AGXT2 (86% identical), dog AGXT2 (85% identical), mouse Agxt2 (85% identical), rat Agxt2 (83% identical), pig AGXT2 (76% identical), tropical clawed frog agxt2 (62% identical), zebrafish agxt2 (56% identical), Drosophila melanogaster CG11241 (51% identical), Caenorhabditis elegans T09B4.8 (45% identical). Paralogues in human: ETNPPL (32% identical), PHYKPL (28% identical), OAT (25% identical), ABAT (20% identical).